GPX1 (glutathione peroxidase 1)
Diseases named in the same sentence as GPX1 in open-access papers (continued):
Sharing a sentence is not in itself a finding about the gene and the disease.
colitis (19 papers, 2013 to 2025). Inflammation of the colon. "It is noteworthy that the GPX1 gene is known to be associated with colitis, indicating its involvement in the regulation of inflammatory signaling pathways." (PMID 38678387, 2024). "Lastly, loss of Prx4 providing resistance to colitis fits the general trend observed when antioxidant enzymes are depleted in colitis models: loss of Prx1, Prx2, and Prx6 and the combined loss of GPx1 and catalase all improved colitis in mouse and rat models." (PMID 36978925, 2023). "Further, Gpx1 activity is associated with enhanced Treg cell activity in mice, and mice deficient in both glutathione peroxidases, Gpx1 and Gpx2, develop spontaneous colitis." (PMID 23776564, 2013). "Furthermore, GPx knockout mice for the widely expressed GPx1 and its epithelium-specific variant GPx2 develop intestinal inflammation and colitis." (PMID 35052541, 2021). "Acetic acid-induced colitis produced a significant decrease in GPX-1 contents in the colonic tissues of the intoxicated group (181.1±8.8 pg/mg of protein), when compared with that of the normal control group (332.2±7.38 pg/mg of protein)." (PMID 40292264, 2025). "Given the study showing the reduced enzymatic activity of GPX and GSH in SOD1 deficiency in a DSS-induced colitis model, we cannot exclude the possibility that a lower expression of GPX1 in our study is the result of reduced SOD in colitis." (PMID 38668322, 2024). "With the antioxidant function of selenoproteins that can play roles in intestinal inflammation, spontaneous colitis can be induced in GPx1 and GPx2 knockout mice." (PMID 35624837, 2022). "In view of the high activity of COX and LOX pathways during inflammatory bowel disease our data therefore provide new insights into the mechanisms of the protective function of GPx1 and GPx2 during colitis as well as inflammation-driven carcinogenesis." (PMID 31765890, 2020). "Based on these data, protective functions of GPx1 and 2 during colitis as well as inflammation-driven carcinogenesis can be anticipated." (PMID 31765890, 2020). "Colitis reduced colonic Sod2, Gpx1, and Prdx1 (peroxiredoxin) by 37%, 29%, and 58%, respectively, compared to the non-colitic control." (PMID 31212794, 2019). "To summarize, colitis resulted in GPx1 gene upregulation and CAT gene downregulation, while HBO2 downregulated SOD1 and further upregulated GPx1 in a tissue-specific manner." (PMID 27656047, 2016). "The results showed that GPx1−/− × Cat−/− Tregs were hyperfunctional and GPx1−/− × Cat−/− mice were resistant to DSS-induced colitis." (PMID 24743300, 2014). "In contrast, inflammatory diseases such as colitis develop spontaneously in GPx-1−/− × GPx-2−/− mice, suggesting that inflammation is augmented." (PMID 24743300, 2014). "Actually in the present study, the frequency of FoxP3+ cells was significantly increased in parallel with significantly attenuated inflammatory reaction in the lesions of DSS-induced colitis in mice with elevated level of ROS due to defects in GPx1 and Cat." (PMID 24743300, 2014). "Mice deficient in both GPx1 and GPx2 spontaneously develop ileocolitis and DSS-induced colitis is more severe in mice deficient in GPx2." (PMID 23977205, 2013). "HBPF diet also increased the gene expression of Pparg and enzymatic antioxidants (Sod1, Sod3 and Gpx1), genes all reported to be involved in promoting an immunosuppressive Treg cell response and to protect against colitis." (PMID 23776564, 2013). "These novel findings are complemented by the demonstration of reduced GPx1 in the colon of mice with DSS-induced colitis, murine colitis induced by knockout of GPx1 and GPx2, and genome-wide association studies that note polymorphisms in antioxidant genes, including GPxs in IBD." (PMID 39695083, 2024). "GPx2 and GPx1 are important regulatory factors of epithelial cells and may affect inflammatory responses, and speculate that GPx1 and GPx2 have certain protective functions in colitis and inflammation-driven carcinogenesis." (PMID 35624837, 2022).
colitis (continued). "Interestingly, the mRNA level of Nrf2 in the colon was not affected by the T cell transfer, although the mRNA expression of SOD2 and Gpx1 was lowered by colitis but maintained by aronia feeding." (PMID 31212794, 2019). "In contrast 15-PGDH, GPx-1/2 and hPGDS were increased in Se-Sup group compared to Se-Def and Se-Ade groups suggesting that Se at different dietary concentrations differentially regulates the inflammation in experimental colitis." (PMID 30063735, 2018). "Gpx1 KO mice are resistant to experimentally-induced inflammatory diseases, whereas Gpx1×Gpx2 double KO mice develop spontaneous inflammatory diseases, such as colitis." (PMID 25275529, 2014). "In our study, administration of Ia.Cr resulted in significant increase in SOD, GPX-1 and CAT activities when compared with the colitis-induced group." (PMID 40292264, 2025). "SOD, GPX-1, and CAT are additional significant reactive oxygen metabolites that have a role in the pathophysiology of colitis." (PMID 40292264, 2025). "Strong correlation of HIF-1α mRNA level to GPx1, SOD1, and IL-6 mRNA expression suggests involvement of HIF-1α in transcriptional regulation of these genes during colonic inflammation and HBO2." (PMID 27656047, 2016). "In the spleen, Nfe2l2, Gclc, Gsr, Sod2, Gpx1, Gpx2, and Prdx1 were not consistently affected by T cell transfer colitis." (PMID 31212794, 2019). "In the MLN, colitis also reduced the expression of Nrf2 (Nfe2l2), γ-glutamylcysteine synthetase (Gclc), glutathione reductase (Gsr), Gpx1, and Gpx2 by 27% to 45% relative to the non-colitic control." (PMID 31212794, 2019). "Moreover, LSE enhanced GPX1 and GPX2 levels in DSS-induced colitis mice, although it was not significant (P > 0.05)." (PMID 35059326, 2021).
bladder cancer (17 papers, 2015 to 2024). "The study concluded that the proline/leucine genotype of GPX1 was correlated with a higher risk of developing bladder cancer when compared with the proline/proline genotype." (PMID 39336970, 2024). "In another study, the genotype of the leucine to proline polymorphism located in codon 198 at GPX1 was determined by PCR in cases of bladder cancer and healthy individuals." (PMID 39336970, 2024). "On the other hand, a significant association between GPX1 genetic polymorphism and the risk of bladder cancer was reported in a few studies." (PMID 36676755, 2023). "It is noteworthy to mention that when polymorphisms of both GPX1 and SOD2 genes were analyzed in combination, the presence of GPX1 Pro allele increased the OR for bladder carcinoma risk (1.55 to 2.16 times)." (PMID 36676755, 2023). "Some systematic reviews and meta-analyses demonstrated that GPX1 Pro198Leu polymorphism significantly increased bladder cancer susceptibility." (PMID 35626163, 2022). "Les termes de recherche suivants et les termes chinois correspondants ont été utilisés : “natural resistance-associated macrophage protein 1 or NRAMP1”, “human glutathione peroxidase 1 or hGPX1”, “polymorphism or variant or mutant”, et “bladder cancer”." (PMID 29187939, 2017). "Single-nucleotide polymorphism (SNP) meta-analysis in a case controlled study shows GPx1 Pro198Leu polymorphism is associated with a significantly increased risk of bladder cancer compared to GPx1 Pro/Pro genotype." (PMID 27023612, 2016). "Therefore, the Leucin allele in GPX1 was found to be a risk allele both for the development of bladder cancer and for having advanced tumor stages in those who developed bladder cancer." (PMID 39336970, 2024). "In addition, the results of a meta-analysis also showed that carriers of one or both GPX1-Leu alleles had an approximately 2-fold higher risk of developing bladder cancer, compared to GPX1 Pro/Pro genotype." (PMID 36676755, 2023). "The results confirmed that the GPX1 genotype may further affect the status of bladder cancer, and the increased risk may be modified by the Ala-9Val MnSOD polymorphism." (PMID 36937410, 2023). "Besides bladder cancer, during the past two decades, GPX1 Pro198Leu polymorphism has been extensively studied in other cancer types, mainly breast, prostate, lung, leukemia, and colon cancers." (PMID 36676755, 2023). "However, individuals with GPX1 Pro198Leu polymorphism have a significantly higher probability of developing bladder cancer than controls in Japanese, Ecuadorian, and Turkish populations." (PMID 35626163, 2022). "Furthermore, within the bladder cancer group, the proline/leucine genotype of GPX1 was more prevalent in cases with stage T2-4 tumors compared with Ta-1 tumors, indicating its association with advanced tumor stages." (PMID 39336970, 2024). "BBM increased the intracellular ROS level by downregulating antioxidative genes such as Nrf2, HO-1, SOD2, and GPX-1 to suppress the progression of bladder cancer, while a novel synthetic BBM derivative, BBMD3, increased the production of ROS in osteosarcoma cells." (PMID 37382506, 2023). "Moreover, bladder cancer development is affected by the genotype of GPx1 which suggests that GPx1 is relevant to bladder cancer progression." (PMID 33884538, 2022). "On the other hand, although GPX1 has not been reported to be involved in ferroptosis, is thought to contribute to worsening prognosis, tumor growth, and treatment resistance in several cancers, including breast and bladder cancer, via its antioxidative activity." (PMID 38182643, 2024).
glioma (17 papers, 2012 to 2025). A benign or malignant brain and spinal cord tumor that arises from glial cells (astrocytes, oligodendrocytes, ependymal cells). "Treatments with 5 and 6 caused a significant decrease in mRNA expression of both GPx1 and GPx4 in all four glioma cell lines." (PMID 33134322, 2020). "Furthermore, we observed an increased risk of glioma occurrence associated with the GPX1 rs1800668 variant (adjusted OR = 1.18; 95% CI = 0.82–1.69)." (PMID 23259684, 2012). "The overexpression of GPx1 has also been negatively correlated with overall survival in several types of cancers such as breast, gastric, glioma, and leukemia." (PMID 39796741, 2025). "Though the high expression of GPX1 and CCN1 both indicated worse prognosis in glioma, only GPX1 was significantly upregulated in GBM compared with normal brain tissue." (PMID 35910786, 2022). "The expression of GPx1 was downregulated in lung after exposure to cigarette smoke in Nrf-2-knockout mice, while, the enhanced Nrf-2 expression increased GPx1 transcription and decreased oxidants generation in glioma stem cells." (PMID 30308475, 2019). "Single nucleotide polymorphisms in SOD2, SOD3, GPX1, and NOS1 were found to significantly increase the risk of glioma development in a Chinese population." (PMID 28108734, 2017). "Using single-locus analysis, we identified four SNPs (SOD2 V16A, SOD3 T58A, GPX1 -46 C/T, and NOS1 3’-UTR) that were significantly associated with the risk of glioma development." (PMID 23259684, 2012). "We examined 16 single nucleotide polymorphisms (SNPs) of 9 antioxidant genes (GPX1, CAT, PON1, NQO1, SOD2/MnSOD, SOD3, and NOS1*2*3) in 384 glioma and 384 control cases in a Chinese hospital-based case–control study." (PMID 23259684, 2012). "Four SNPs (SOD2 V16A, SOD3 T58A, GPX1 -46 C/T, and NOS1 3’-UTR) demonstrated a significant association with glioma risk, as determined by the dominant model (variant-containing genotypes versus common homozygote)." (PMID 23259684, 2012). "In glioma, Auranofin induced mitochondrial suppression through the GPX1 pathway." (PMID 35910786, 2022). "Gpx1 has been shown to regulate the sensitivity of glioma cell to oxidative stimuli." (PMID 36289655, 2022). "Furthermore, miR-153 was demonstrated to downregulate GPx1, leading to radioresistance in glioma stem cells." (PMID 35892591, 2022). "Downregulated miR-153 expression in glioma stem cells (GSCs) promotes its target gene, nuclear factor-erythroid 2-related factor-2 (Nrf-2), which cascades to activate GPX1 transcription and reduce ROS levels, resulting in further enhancement of the radioresistance and stemness in GSCs." (PMID 35626163, 2022). "Additionally, miR-153 overexpression decreases the radioresistance and stemness of glioma stem cells by targeting the Nrf-2/GPx1/ROS pathway." (PMID 30305135, 2018). "Glioma stem cell lines expressing active GPx1 might decrease ROS level in Glioma CSCs and resist ROS/RNS-mediated cell death, thus creates a carcinoma stem cell niche." (PMID 29108391, 2017). "In GSCs, Nrf2 expression is upregulated compared to non-stem glioma cells, leading to increased glutathione peroxidase 1 (GPx1) transcription and decreased ROS levels, which contributes to their radio-resistance." (PMID 40214466, 2025). "We plotted the PSI (percent spliced in) percentage of intron retention of GPX1 against the expression data of NONO in glioma from the TCGA dataset to examine the splicing relationship between the two genes." (PMID 35910786, 2022). "Collectively, these data demonstrated that miR-153 expression was down-regulated in GSCs compared with that of non-GSCs glioma cells, which contributed to enhanced Nrf-2 expression resulting in activation of GPx1 transcription." (PMID 26124081, 2015). "GPx1 protein expression in non-GSCs glioma cells was significantly reduced compared with that of GSCs." (PMID 26124081, 2015). "We next investigated the enzymatic activities of catalase, MnSOD and GPx1 in GSCs and non-GSCs glioma cells." (PMID 26124081, 2015).
glioma (continued). "Real-time RT-PCR analysis indicates that non-GSCs glioma cells displayed significantly lower GPx1 mRNA levels than GSCs, which corresponded to that of protein expression and enzymatic activity." (PMID 26124081, 2015). "Assays for GPx1 activity showed that non-GSCs glioma cells displayed significantly lower basal GPx1 activity than GSCs." (PMID 26124081, 2015). "We found that non-GSCs glioma cells displayed significantly lower basal GPx1 expression and activity than GSCs." (PMID 26124081, 2015). "To gain insights in the possible mechanisms involved in the regulation of GPx1 expression, we first analyzed GPx1 mRNA expression in GSCs and non-GSCs glioma cells." (PMID 26124081, 2015). "Therefore, GPX1 mRNA, protein, and enzyme activities in GSCs are all significantly higher than those in non-GSCs glioma cells." (PMID 35626163, 2022).
gastric cancer (15 papers, 2017 to 2024). A primary or metastatic malignant neoplasm involving the stomach. "The promoter region of GPx1 has GC-boxes for Sp1 family transcription factors, and aberrant hypermethylation of GPx1 promoter DNA is implicated in its downregulation in gastric cancer." (PMID 38539790, 2024). "Loss (reduction) of GPX1 mRNA and protein expressions due to aberrant hypermethylation of the promoter region in gastric cancer cell lines and tissues is significantly associated with aggressiveness and poor survival in gastric cancer patients." (PMID 35626163, 2022). "On the contrary, in a previous study that included patients with gastric cancers, low expression of GPX1 was associated with aggressive tumors." (PMID 34943522, 2021). "In patients with gastric cancer, low expressed GPx1 tumors were associated with aggressiveness and poor survival." (PMID 28536671, 2017). "Next, we conducted scratch and transwell assays to evaluate the role of GPX1 in gastric cancer migration." (PMID 37862109, 2023). "To further investigate the role of GPX1 in gastric cancer development, we transfected GPX1 siRNA into human gastric cancer cell lines SGC-823 and SGC-7901." (PMID 37862109, 2023). "However, several studies have demonstrated the role of GPx1 as a tumor suppressor in some pancreatic and gastric cancers." (PMID 39125992, 2024). "In addition, we measured GPx2 and GPx1 expression in gastric cancer tissues and paired paracancerous tissues by Western blotting." (PMID 37138031, 2023). "However, reduced expression of GPx1 is detected in thyroid cancer, gastric cancer, and colorectal cancer, whereas GPx1 is highly expressed in kidney cancer and pancreatic cancer." (PMID 38202704, 2023). "Polymorphism in GPX1 gene had no impact on survival in studies concerning breast and gastric cancer." (PMID 34200699, 2021). "Like GPx1, GPx3 exhibits a dual role in cancer, and these seemingly contradictory results may be closely related to ROS; it serves as a pro-survival protein in myeloid leukemia and as a tumor suppressor in lung, ovarian, and gastric cancers." (PMID 39125992, 2024). "However, the expression of GPx1 has been reported to be down-regulated in thyroid cancer, colorectal cancer, and gastric cancer, whereas GPx1 has been demonstrated to play an oncogenic role in kidney cancer, pancreatic cancer, and laryngeal squamous cell carcinoma." (PMID 32571353, 2020). "CircMAP2K2 regulates the PCBP1/GPX1 axis through proteasome‐mediated degradation, resulting in an epithelial‐to‐mesenchymal transition (EMT)‐like phenotype, and activated AKT/GSK3β signaling pathway enhances proliferation and metastasis of gastric cancer." (PMID 37752765, 2023).
hepatocellular carcinoma (15 papers, 2013 to 2024). A malignant tumor that arises from hepatocytes. "The levels of GPx1 and 2 and Prdx1, 3, and 5 in hepatoma cells were increased compared to hepatocyte-like cells, while GPx3 was markedly reduced." (PMID 37189460, 2023). "The mechanobiology of oxidative stress-related genes (i.e., catalase; superoxide dismutase 1, SOD1; and glutathione peroxidase 1, GPx-1) upon exposure to pure AgNPs in human hepatoma cells has been studied; these genes have been found to be implicated in maintaining antioxidant defense capacity." (PMID 32178476, 2020). "We investigated whether Lp(a) alone could promote changes in the antioxidant enzymes, GPx1, Prdx6, and Sod1, by incubating purified Lp(a) with human hepatoma cells." (PMID 30596094, 2018). "EGCG has been shown to downregulate GPX1 in human hepatocellular carcinoma BEL7402/5-FU cells." (PMID 25922640, 2015). "The aim of this work was to test in vitro the effect of sodium selenite on the human hepatoma cell lines, HepG2 and Huh7, to assess its effect on the expression of GPX1, SELK and SELENBP1 and also to evaluate its action on inflammation determinants such as cytokines." (PMID 23442931, 2013). "SBP1 had been reported to inhibit GPX1 activity to promote oxidative stress and reciprocally regulate hypoxia-inducible factor-1α (HIF-1α) in the oxidative stress model of hepatoma cells stimulated by H2O2." (PMID 31019652, 2019). "Hepatocellular carcinoma tissues collected at Tottori University Hospital were used to determine the mRNA expression levels of CD44, NOTCH3, and GPX1." (PMID 30636370, 2019). "GPX1, SOD1, and CAT convert superoxide radicals (O2•−) produced in the mitochondrial respiratory chain into O2 and H2O, while PGLS inhibits the expression of ROS in human hepatocellular carcinoma cells, thereby inducing apoptosis." (PMID 38731375, 2024). "The goal of our research was to investigate whether the treatment with selenite shows functional effects on GPX1, SELK and SELENBP1, which belong to two different classes of selenium containing molecules, and on the hepatoma cell cytokinome." (PMID 23442931, 2013). "In hepatocellular carcinoma (HCC), selenium-binding protein 1 (SBP1) and GPX1 formed nuclear bodies and colocalized under oxidative stress." (PMID 24228025, 2013).